SRP14 (signal recognition particle 14)
Description:
Component of the signal recognition particle (SRP) complex, a ribonucleoprotein complex that mediates the cotranslational targeting of secretory and membrane proteins to the endoplasmic reticulum (ER). SRP9 together with SRP14 and the Alu portion of the SRP RNA, constitutes the elongation arrest domain of SRP. The complex of SRP9 and SRP14 is required for SRP RNA binding.
Synonyms: ALURBP; MGC14326
Tractability: Small molecule: a structure with a bound ligand is known. Antibody: its Gene Ontology location is reachable by antibodies, with high confidence. PROTAC: ubiquitination databases record sites on it; its protein half-life has been measured.
Gene: Protein-coding gene on chromosome 15 (40,035,690 to 40,039,181, reverse strand). Ensembl gene ENSG00000140319.
Subcellular location: Cytoplasm
Subcellular location (Human Protein Atlas): Nucleoli; Nucleoplasm
Pathways (Reactome):
Immune System: Neutrophil degranulation
Metabolism of proteins: SRP-dependent cotranslational protein targeting to membrane
Gene Ontology:
Molecular function: protein binding; RNA binding; 7S RNA binding; endoplasmic reticulum signal peptide binding
Biological process: protein targeting to ER; cotranslational protein targeting to membrane; SRP-dependent cotranslational protein targeting to membrane, signal sequence recognition; SRP-dependent cotranslational protein targeting to membrane, translocation; SRP-dependent cotranslational protein targeting to membrane
Cellular component: nucleus; signal recognition particle, endoplasmic reticulum targeting; cytoplasm; cytosol; extracellular region; ficolin-1-rich granule lumen; secretory granule lumen; signal recognition particle
Genetic constraint (gnomAD): Loss-of-function variants: 1 observed, 14.72 expected, observed/expected ratio (o/e) 0.068, 90% interval 0.023 to 0.32. The upper end of that interval is the gene's LOEUF score, 0.32, which puts it in group 1 of 6, group 1 being the genes least tolerant of losing a copy. Missense variants: 99 observed, 139.34 expected, observed/expected ratio (o/e) 0.71, 90% interval 0.6 to 0.84. Synonymous variants: 58 observed, 50.49 expected, observed/expected ratio (o/e) 1.15, 90% interval 0.93 to 1.43.
Homologues: Orthologues: guinea pig SRP14 (75% identical), mouse Srp14 (72% identical), rat Srp14 (72% identical), tropical clawed frog srp14 (66% identical), zebrafish srp14 (66% identical), rat AABR07068253.1 (65% identical), pig SRP14 (57% identical), rabbit SRP14 (50% identical), Caenorhabditis elegans F25G6.9 (36% identical).
Diseases named in the same sentence as SRP14 in open-access papers:
SRP14 is named in the same sentence as 18 diseases in open-access papers, as found by Europe PMC text mining. Sharing a sentence is not in itself a finding about the gene and the disease. The quoted sentences say what the papers report.
breast carcinoma (4 papers, 2013 to 2022). "It has been indicated that in breast cancer, deficiencies of SRP9 and SRP14 activate RIG-1, which further causes an interferon response, increases inflammation, and leads to breast cancer metastasis." (PMID 36518216, 2022).
endometriosis (3 papers, 2023 to 2025). The growth of functional endometrial tissue in anatomic sites outside the uterine body. "Expression of several of these genes (LINC00339, CDC42, GDAP1, FGD6, SRP14) has been associated with risk of endometriosis previously." (PMID 37587191, 2023). "Finally, endometriosis-associated mQTLs associated with expression of GDAP1, SRP14, and HOXB9 are in moderate LD (r2 > 0.6) with SNPs significantly associated with endometriosis and with eQTLs for these genes in the recent endometriosis meta-analysis." (PMID 37587191, 2023). "The clustering analysis, which reveals pain-related genes (SRP14/BMF, GDAP1, MLLT10, BSN, and NGF), further solidifies the genetic basis for the chronic and often debilitating pain experienced by patients with endometriosis." (PMID 41516028, 2025).
acute myeloid leukemia (2 papers, 2021 to 2022). Acute myeloid leukemia (AML) is a group of neoplasms arising from precursor cells committed to the myeloid cell-line differentiation. "This study aimed to determine and verify the prognostic value and potential functional mechanism of signal recognition particle 14 (SRP14) in acute myeloid leukemia (AML) using a genome-wide expression profile dataset." (PMID 33985510, 2021). "Signal recognition particle 14 (SRP14) plays a role in OS in acute myeloid leukemia patients." (PMID 35027588, 2022).
endometrial cancer (2 papers, 2020 to 2021). Primary or metastatic malignant neoplasm involving the endometrium (mucous membrane that lines the endometrial cavity). "The expression of signal recognition particle 14 (SRP14) has previously been reported to be closely related to endometrial cancer and to serve as a reference gene for AML when combined with other genes." (PMID 33985510, 2021).
endometrial tumors (2 papers, 2019 to 2020). "Three of these associations were observed in whole blood (SNX11, HOXB2 and SRP14) and one in endometrial tumors (BCL11A)." (PMID 31561579, 2019).
latent infection (2 papers, 2018 to 2021). "To assess the role of SRP14 in controlling latent infection, we tested the effect of its overexpression on virus reactivation in a T-cell line model of latent infection, using the J-Lat 10.6, 8.4 and A2 clones." (PMID 34194479, 2021). "Out of the 243 interactions identified, knockdown of SRP14 (Signal Recognition Particle 14) negatively affected tat mRNA processing and translation as well as Tat-mediated transactivation, which led to an increase in latent infection." (PMID 34194479, 2021). "Altogether, these data are consistent with direct binding of SRP14, HMGB3 as well as PTB to MS RNA highlighting a potential role of these RNA binding proteins in controlling Tat expression during latent infection." (PMID 34194479, 2021). "On the other hand, a dramatic increase in latent infection was seen after knockdown of TOP2A, SRP14, HNRNPH1, DDX1, and HNRNPL (blue bars)." (PMID 34194479, 2021).
glioblastoma (1 paper, 2022). The most malignant astrocytic tumor (WHO grade IV). "Interestingly, the level of SRP14 protein in glioblastoma cells is increased by CYP17A1, an enzyme implicated in steroidogenesis." (PMID 36361638, 2022).
Graves disease (1 paper, 2017). Graves' disease is an autoimmune disorder that leads to overactivity of the thyroid gland (hyperthyroidism).It is caused by an abnormal immune system response that causes the thyroid gland to produce too much thyroid hormones. "Interestingly, upregulated intensities of SRP14 were found in the protein export pathway in Thyroid-associated ophthalmopathy, a disease which represents the first extrathyroidal manifestation of Graves’ disease, a chronic autoimmune disorder affecting the orbit around the eye." (PMID 28740252, 2017).
HIV-1 infection (1 paper, 2021). The type species of lentivirus and the etiologic agent of acquired immunodeficiency syndrome (AIDS). "The effect of SRP14 and HMGB3 KD on use of SA3 is consistent with the effects of these proteins on latent and productive infection, suggesting an important role of these proteins in Tat mRNA processing and regulation of HIV-1 infection." (PMID 34194479, 2021).
leukaemia (1 paper, 2024). "The strongest association was for SRP14 with leukaemia [1.22 (1.16–1.28)] followed by KRT18 for liver cancer [1.29 (1.18–1.42)], CD1C for NHL [1.11 (1.06–1.16)] and TNR for lung cancer [0.92 (0.89–0.95)." (PMID 38750076, 2024). "SRP14 was associated with the risk of leukaemia in both observational and exGS analyses and was more strongly associated with the risk of leukaemia in people diagnosed within the first three years." (PMID 38750076, 2024). "After correcting for multiple testing (0.05/533 exGS tests), we identified 28 associations, including 24 for NHL, 2 for leukaemia (SRP14, TREML2), 1 for both liver (KRT18) and lung cancer (TNR)." (PMID 38750076, 2024). "Given that cis-pQTL did not support a role for SRP14 with leukaemia risk, it is therefore possible that SRP14, as a biomarker of imminent leukaemia diagnosis, may indicate constitutively active JAK2." (PMID 38750076, 2024). "SRP14 has a well-described role in protein targeting in the endoplasmic reticulum, has a high probability of being loss-of-function intolerant (pLi), and is essential for leukaemia and lymphoid malignancy cell survival, as shown using CRISPR knockout models." (PMID 38750076, 2024).
Sepsis (1 paper, 2022). Sepsis is defined as life-threatening organ dysfunction caused by a dysregulated host response to infection. "SRP14, which traffics secretory proteins through the endoplasmic reticulum, and ELOA, a subunit of the transcription factor B (SIII) complex, may aid protein synthesis by immune cells during sepsis." (PMID 36572854, 2022).
viral infections (1 paper, 2022). "Additional host factors that were significantly enriched include those described for other viral infections, such as negative-stranded RNA virus vesicular stomatitis virus (VSV) (ARFRP1, SYS1, and YKT6) and the human immunodeficiency virus (HIV) (SRP14, DYRK1A, and IL2RA) (33, –, 37)." (PMID 35502904, 2022).
infection (3 papers, 2018 to 2024). The state of being infected such as from the introduction of a foreign agent such as serum, vaccine, antigenic substance or organism. "Interestingly, these effects correlated with the levels of the proteins in rCD4+ T cells following HIV‐1 infection as we observed a decrease in SRp14 levels while HMGB3 peaked very quickly after infection in rCD4+." (PMID 30051631, 2018). "Interestingly, two genes, SRP14 and HMGB3 have not been previously reported to play a role in the regulation of HIV-1 replication and their knockdown here had very marked effects on latent and productive infection, respectively." (PMID 34194479, 2021).
cancer (1 paper, 2019). A tumor composed of atypical neoplastic, often pleomorphic cells that invade other tissues. "Consistent with our observation that endometrial cancer risk CVs were associated with increased SRP14 expression, stress granules promote cell survival and cancer cell fitness, and their components are upregulated in tumors." (PMID 31561579, 2019).
SRP14 also shares sentences with these, for which no sentence is quoted: hepatoma (1 paper); liver cancer (1); lung carcinoma (1); Thyroid-associated ophthalmopathy (1).